NOTCH1 (notch receptor 1)
Diseases named in the same sentence as NOTCH1 in open-access papers (continued):
Sharing a sentence is not in itself a finding about the gene and the disease.
colon carcinoma (84 papers, 2010 to 2025). "The expression of Notch-1 was significantly associated in colon cancer with the lymph node metastasis, TNM stage, and degree of differentiation (p < 0.05), not with age, gender, serous membrane invasion,and tumor size (p > 0.05)." (PMID 39691600, 2024). "Several studies have linked the increase in proliferation of colon cancer cells to Notch1 signaling; particularly, Notch1 regulates cell proliferative abilities and regulates apoptosis in cells." (PMID 35740666, 2022). "This means that β-catenin is regulated in many ways, for example, NOTCH1 plays a key role in the Wnt pathway, and activation of NOTCH1 is associated with the translocation of β-catenin to the nucleus in colon cancer." (PMID 31689969, 2019). "In this context, the analysis of primary colon cancer samples showed that the activation of NOTCH1 is associated with the translocation of β-catenin in the nucleus." (PMID 29652830, 2018). "We observed the NOTCH1 A465T variant in colon cancer [DOID:219], malignant glioma [DOID:3070], esophageal cancer [DOID:5041], head and neck cancer [DOID:11934], pharynx cancer [DOID:0060119], and brain cancer [DOID:1319]." (PMID 29531238, 2018). "We subsequently investigated the association of NOTCH1 expression in resected tumor tissues samples with the clinicopathological features and prognosis of colon cancer patients." (PMID 28947978, 2017). "We recently found that an extra-pure formulation of EPA as Free Fatty Acid (EPA-FFA) protects from colon cancer development in a mouse model of Colitis-Associated Cancer (CAC) through modulation of NOTCH1 signalling." (PMID 26864323, 2016). "Additionally, hypoxia-induced cell migration and invasion in triple-negative breast cancer cells and colon cancer cells have been linked to the Notch1/ORAI1/SOCE/NFAT4 pathway." (PMID 38672434, 2024). "Therefore, combined curcumin and luteolin synergically inhibit colon cancer development by suppressing cell proliferation, necrosis, and migration associated with Notch1 and TGF-β pathways." (PMID 35740666, 2022). "Another example of the shift of pro-survival pathways activation was described when inhibition of Notch1 with different GSIs led to transient activation of ERK 1/2 signaling that made the Notch1-positive subpopulation of colon cancer cells more susceptible to cisplatin-induced cell death." (PMID 34680255, 2021). "Specifically, NOTCH1 expression is inversely correlated with survival rates in colon cancer patients, underscoring its significance as a prognostic marker." (PMID 40754247, 2025). "A recent study has reported that vitamin D (supposedly calcitriol) decreases NOTCH1 protein expression in human SW480 colon carcinoma cells." (PMID 38684650, 2024). "Notch-1, as one of the important members of the Notch family, has gradually become a new trend in the study of colon cancer." (PMID 39691600, 2024). "Clinicopathological factors according to the expression of Numb and Notch-1 protein in 110 patients with colon cancer tissues." (PMID 39691600, 2024). "For instance, quercetin suppresses the Notch-1 signaling pathway, which lowers the proliferation of colon cancer cells and colon cancer stem cells and selectively generates the KRAS mutations that cause apoptosis in colorectal cancer cells." (PMID 39201782, 2024). "At the same time, Notch-1 and Numb are targeted to provide a possible molecular basis for the targeted therapy and prognosis of colon cancer." (PMID 39691600, 2024). "NOTCH1 amplifications are present in 0.08% of all colon carcinoma patients; NOTCH1 alterations are thought to drive progression and metastatic seeding by TGF-beta signaling." (PMID 36790480, 2023).
colon carcinoma (continued). "For instance, a previous study concluded that colon cancer cells with DDR1 overexpression have the ability to survive more due to the activation of Notch1 which stimulates the expression of pro-survival genes Hes1 and Hey2." (PMID 37271822, 2023). "In one study, it was discovered that miR 139-5p, which targets NOTCH-1, and microRNA-34a, which inhibits the enzyme lactate dehydrogenase, sensitize colon cancer cells to 5-fluorouracil." (PMID 37760489, 2023). "According to Chulan Kwon’s study, Notch1 was able to physically interact with unphosphorylated (active) β-catenin in stem and colon cancer cells, and negatively regulate the post-translational accumulation of active β-catenin protein." (PMID 36834623, 2023). "Withaferin-A also possesses its apoptotic action on human colon cancer cells through inhibition of the Notch-1 signalling pathway and down-regulating pro-survival pathways, such as Akt/NF-κB/Bcl-2 in three colon cancer cell lines (HCT-116, SW-480, and SW-620)." (PMID 37063285, 2023). "In another report, the effect of withaferin A on apoptosis has been observed in three different human colon cancer cells, through modulating the Notch-1 signaling pathway and the downregulation of Akt/NF-κB/Bcl-2." (PMID 37259311, 2023). "Honokiol, a traditional Chinese and Japanese herbal therapeutic, inhibited Notch pathway components, including Notch-1 and -2, Jagged-1, Hes-1, and subunits of the gamma secretase complex in melanoma, hepatocellular carcinoma, and colon cancer cells." (PMID 35408894, 2022). "In CRC, genistein can inhibit colon cancer cell migration by reversing EMT through inhibition of the Notch1/NF-κB/slug/E-cadherin pathway, suggesting its potential as an antimetabolite for colon cancer." (PMID 36158694, 2022). "In the treatment of colon cancer, when quercetin was combined with ionizing radiation (IR) therapy, colon cancer stem cells as target cells can have antitumor effects by inhibiting Notch-1 signaling." (PMID 35684449, 2022). "EGCG inhibited Notch-1 in neuroblastoma, cholangiocarcinoma, and colon cancer cell lines, and in head and neck squamous cell carcinoma CSCs." (PMID 35408894, 2022). "Withaferin A has also demonstrated anticancer activity against colon cancer by targeting and downregulating Notch-1 signaling via targets such as Hey-1 and Hes-1 and concurrently suppressing crosstalk between Notch-1 and Akt/mTOR pathways." (PMID 35335986, 2022). "This synergistic anti-colon cancer effect by this combination involves regulating the Notch1 and transforming growth factor- beta (TGF-β) pathways as well as inducing necrosis both in cells and tumors." (PMID 35740666, 2022). "ASR490 effectively inhibited the growth of HCT116 and SW620 colon cancer cell lines by downregulating Notch1 signaling." (PMID 35164150, 2022). "Improved sensitivity of colon cancer cells to 5-FU was achieved also through targeting the epigenetic machinery with STRAP silencing that restored PCR2 inhibitory activity on Notch1 expression." (PMID 34680255, 2021). "Conversely, Notch1 functions as a tumor suppressor to transform high-grade adenomas into low-grade ones in murine models of colon cancer by epigenetically suppressing Wnt pathway target genes." (PMID 33681228, 2021). "Consistently, tumor explants derived from colon cancers sensitive to GSI PF-03084014 showed higher levels of Notch1 and Wnt/β-catenin signaling components compared with the resistant samples and GSI treatment, affecting the activation of both pathways." (PMID 34680255, 2021). "In colon cancer, miR-34c-3p inhibits self-renewal and differentiation of tumor stem cells by targeting Notch1." (PMID 35004298, 2021). "It was suggested that the knockdown of Disheveled-3 re-sensitized colon cancer cells to methotrexate by attenuating Notch1 signaling; however, this molecular marker was considered as a signature associated with CSC." (PMID 34680255, 2021).
colon carcinoma (continued). "For example, the activation of Notch1 in colon cancer inhibits apoptosis by repressing p27 expression." (PMID 33681228, 2021). "Not only Notch1 but also Notch3 knockdown suppressed spheroid formation as well as Oct-4 and Lgr5 expression and improved 5-FU resistance in another colon cancer cell model." (PMID 34680255, 2021). "Microarray analysis showed that Notch1 and Hes1 were increased during the development from physiological healthy colonic mucosa to colon cancer, whereas Notch2, Jag1 and Dll3 remained unchanged." (PMID 32796631, 2020). "Taken together, these data suggest that C-B and C-I interact with Notch-1 and suppress colon cancer growth and stemness." (PMID 31992775, 2020). "Previous study showed that inhibition of NOTCH-1 by lentiviral-encoding NOTCH-1 siRNA can effectively suppress the growth and proliferation of colon cancer cells and promote cell apoptosis." (PMID 32612457, 2020). "As Notch-1 protein is upregulated in colon cancer, our efforts turned to elucidate the mechanisms of Notch inhibition." (PMID 31992775, 2020). "Consistently with our results in Apc mutant adenomas, Notch1+ colon tumour cells were also undifferentiated and proliferative, as they rapidly produced a clonal progeny, evident at 15 days after induction." (PMID 30696875, 2019). "We show that Notch1-labeled cells represent a distinct population of CSCs within both intestinal and colon tumours, which contributes to tumour growth by clonal expansion and generates intra-tumoural heterogeneity." (PMID 30696875, 2019). "The presence of uniformly scattered GFP+ cells 24 hours post-tamoxifen in all colon tumours analysed demonstrated that Notch1 is also expressed in chemically induced colon tumours." (PMID 30696875, 2019). "Withaferin-A (WA), a bioactive compound derived from Withania somnifera, inhibits Notch-1 signaling and cell proliferation in three colon cancer cell lines." (PMID 31915510, 2019). "A 2-month chase showed that Notch1-derived clones had considerably grown, suggesting that Notch1+ colon tumour cells self-renew, like their small intestinal counterparts." (PMID 30696875, 2019). "On the other hand, neutralizing anti-NOTCH1 antibodies blocked the growth of xenografts from colon cancer cells." (PMID 29652830, 2018). "In this study, we demonstrated that GEN can inhibite proliferation and induce apoptosis of colon cancer cells by reversal of EMT via a Notch1/NF-κB/Slug/E-cadherin pathway." (PMID 29202800, 2017). "In human colon cancer Notch1-related signaling also positively regulates tumor growth by promoting proliferation and survival of cancer stem cells and colon cancer cells." (PMID 28915655, 2017). "First, we examined the distribution of β-catenin and NOTCH1 in colon cancer tissue samples using co-immunohistochemistry." (PMID 28947978, 2017). "We examined the localization of NOTCH1 in 189 colon cancer tissue samples using immunohistochemistry." (PMID 28947978, 2017). "Our findings indicate that the role of NOTCH1 in colon cancer progression merits further investigation." (PMID 28947978, 2017). "In colon cancer, miR-34a suppresses cancer stem cells self-renewal and differentiation by targeting Notch1." (PMID 29037220, 2017). "Notch1 was also responsible for the development and increased growth of implanted colon cancers in vivo." (PMID 29104587, 2017). "The association between NOTCH1 and colon cancer was confirmed by the results of experiments using SW480 human colon cancer cells, which express high levels of β-catenin." (PMID 28947978, 2017). "Notch1, Dll-1 and Jagged-1 expression were also assessed in stable Kaiso-depleted colon cancer cells and isolated intestinal epithelial cells using real time PCR and western blotting." (PMID 28637464, 2017). "The present study demonstrated that genistein suppressed the migration of colon cancer cells by reversal the EMT via suppressing the Notch1/NF-κB/slug/E-cadherin pathway." (PMID 29202800, 2017).
colon carcinoma (continued). "Studies have shown that miR-144 can also suppress the expression of the tumor suppressor, phosphatase and tensin homolog (PTEN) and mammalian target of rapamycin (mTOR) and inhibit the growth of colon cancer cells in a Notch-1-dependent manner." (PMID 26826553, 2016). "At relatively high concentrations, (10–20 μg/ml), the MAb affected Notch1 signaling in the breast and colon cancer cell lines." (PMID 26046801, 2015). "In colon cancer stem cells (CCSCs), miR34a demarcates self-renewal and differentiation by targeting Notch1 3′ untranslated regions." (PMID 26062441, 2015). "A possible role for similar high Notch1 expression in the breast and colon cancer cells was investigated." (PMID 26046801, 2015). "miR-139-5p plays a pivotal role in colon cancer through inhibiting cell proliferation, metastasis, and promoting apoptosis and cell cycle arrest by targeting oncogenic NOTCH1." (PMID 24885920, 2014). "Subsequent functional validation revealed the decreased cell proliferation when NOTCH1 was downregulated in colon cancer cells (P < 0.0001)." (PMID 24885920, 2014). "We therefore examined the expression levels of NOTCH1~4 in 27 pairs of colon tumors and adjacent normal tissues." (PMID 24244701, 2013). "In addition, miR-34a has an inhibitory effect on NOTCH1, NOTCH2, and NOTCH4 expression in pancreatic ductal carcinoma, whereas, in colon carcinoma, its inhibition rescued the expression of NOTCH1, NOTCH2, and BCL2." (PMID 40149537, 2025). "In colon cancer and metastasis lymph node tissues, the positive expression rate of Numb was significantly lower than those in the adjacent normal tissue; the positive expression rate of Notch-1 was significantly higher than that in the adjacent normal tissue." (PMID 39691600, 2024). "Cucurbitacin B and I, decrease the expression of Notch receptors and ligands, repressing the activity of gamma-secretases, suppressing NICD production, binding to Notch1, subsequently repressing downstream genes of Notch, inhibiting tumor growth in colon cancer." (PMID 39092224, 2024). "However, the mechanism of Notch-1 and Numb in the lymph node metastasis of colon cancer needs further study." (PMID 39691600, 2024). "Comparing colon cancer tissue or lymph node metastases with tumor adjacent tissue, the positive expression rate of Numb was significantly decreased, while the positive expression of Notch-1 was significantly increased in colon cancer tissue or lymph node metastases (both p<0.05)." (PMID 39691600, 2024). "Therefore, the combination of luteolin and curcumin synergistically exerts anti-colon cancer through regulating Notch1 and TGF-β pathways and inducing necrosis." (PMID 35740666, 2022). "Our results in organoids from TNBC and colon cancer, two tumor types which can suppress immune responses, suggest that Notch1 reactivation via Cbl-b inhibition could be a promising strategy to sensitize “cold” immunosuppressive tumors to cancer immunotherapy." (PMID 36090975, 2022). "Jagged-1, a ligand of Notch1, contributes to metastasis in colon cancer." (PMID 35740666, 2022). "Therefore, the inhibitory effect in colon cancer by combined curcumin and luteolin is at least due to Notch1 downregulation." (PMID 35740666, 2022). "However, a GSI DAPT or Notch1 knockdown improved radiation sensitivity of colon cancer cells directly by affecting the Notch1/HES1 axis, leading to enhanced irradiation-induced DNA damage and attenuated radiation-triggered DNA-PK activity." (PMID 34680255, 2021). "Additionally, HNK sensitized colon cancer cells to ionizing radiation through downregulation of Notch1." (PMID 34680255, 2021). "Among the Notch receptor family (Notch1–4), Notch1 plays a major role in colon cancer." (PMID 32630477, 2020). "The Notch 1 expression was expressed in 58% of the colon cancer patients(n = 462)." (PMID 31263186, 2019).
colon carcinoma (continued). "Conversely, a few studies have reported decreased Hes-1 levels in colon carcinomas compared with adenomas, indicating that the involvement of Notch-1 signaling in the initiation and development of CRC remains unclear and controversial." (PMID 30323897, 2018). "In summary, our findings reveal a novel role for epithelial Notch-1 in protecting from mucinous colorectal adenocarcinoma and open avenues for the development of personalized medicine and targeted therapeutics to be tailored to specific types of colon cancers." (PMID 30323897, 2018). "The expression of NOTCH1 has been reported to be up-regulated in colon cancer tissue." (PMID 28947978, 2017). "Further investigation into the role of NOTCH1 in colon cancer might help to elucidate its role in the Wnt signaling pathway." (PMID 28947978, 2017). "In approximately 50% of the colon cancer samples, NOTCH1 was strongly expressed in the nucleus." (PMID 28947978, 2017). "Induction of Notch1 transformed high-grade adenoma into low-grade adenoma in an APCMin mouse model of colon cancer and suppressed the expression of Wnt target genes through epigenetic modification connected with recruitment of histone metylotransferase SET domain bifurcated 1 (SETDB1)." (PMID 29104587, 2017). "Our data revealed that NOTCH1 and β-catenin co-localize in the colon cancer cells." (PMID 28947978, 2017). "Furthermore, NOTCH1 knockdown significantly inhibits proliferation and colony formation in colon cancer cell lines." (PMID 28947978, 2017). "In the majority of the colon cancer tissue samples, NOTCH1 and β-catenin were co-localized." (PMID 28947978, 2017). "Here, we demonstrated that NOTCH1 acts as an oncogene in colon cancer by activating Wnt signaling." (PMID 28947978, 2017). "Moreover, the proliferation of human colon cancer cells by withaferin-A was attenuated due to the decreased Notch-1 expression." (PMID 26959007, 2016). "miR-34a suppresses self-renewal and differentiation by targeting Notch1 in colon cancer stem cells." (PMID 26902416, 2016). "A previous study reported that colonic cancer cells may upregulate Notch1 as a protective mechanism in response to chemotherapy." (PMID 25936357, 2015). "Knockdown of NOTCH1 caused a significant reduction in cell viability and an increased G0/G1 phase in HCT116 (P < 0.0001), indicating the potential oncogenic function of NOTCH1 in colon cancer." (PMID 24885920, 2014). "This study found that the expression of Notch-1 protein in colon cancer tissues with lymph node metastasis was higher than that in colon cancer tissues without lymph node metastasis, suggesting that the overexpression of Notch-1 protein may promote lymph node metastasis of colon cancer." (PMID 39691600, 2024). "Finally, their study suggested that a combination of IR (5 Gy) and quercetin (20 mM) could be a novel therapeutic approach in colon cancer by suppressing the Notch-1 signaling pathway in CSCs." (PMID 35462903, 2022). "Therefore, downregulation of the Notch1 signaling pathway may be an excellent approach to colon cancer therapy." (PMID 35740666, 2022). "Interestingly, NOTCH1 was shown to activate the WNT/β-catenin signaling pathway in colon cancer." (PMID 29652830, 2018). "However, additional molecular functions of NOTCH1 in colon cancer have yet to be characterized." (PMID 28947978, 2017). "However, it has been shown that the Mastermind-like 1 co-activator of Notch pathway can bind to the promoters of Cyclin D1 and Myc in colon cancer cell lines and these molecules are activated directly by Notch1 in other types of cancer and possibly by Cyclin D1 in CRC." (PMID 28086833, 2017). "However, to the best of our knowledge, there have been no reports of NOTCH1 mutations in colon cancer." (PMID 28947978, 2017). "WA inhibited Notch1 cleavage, downregulated AKT pathway in a Notch-downstream way, and induced apoptosis of colon cancer cells." (PMID 34680255, 2021).